STAT3 (signal transducer and activator of transcription 3)
Diseases named in the same sentence as STAT3 in open-access papers (continued):
Sharing a sentence is not in itself a finding about the gene and the disease.
intestinal cancer (5 papers, 2020 to 2022). "This protein also has many roles in cancer progression and several tumors such as prostate, lung, breast, and intestine cancers that are characterized by strong STAT3-dependent transcriptional activity." (PMID 34440160, 2021). "Apart from the opposing effects of Mir34a and Csf1r on proliferation, apoptosis and STAT3 signaling, their antagonistic effects on the tumor-environment and intestinal cancer stem cells might also be responsible for the compensatory effect of deleting both genes." (PMID 36147476, 2022).
intestinal inflammation (5 papers, 2018 to 2025). "Taken together, these results indicate IL-6/STAT3 pathway plays an important role in the regulation of P2RY13-aggravated intestinal inflammation." (PMID 35982893, 2022). "Activation of this chemokine pathway further promotes an acute immune response and inflammation via the Stat proteins; Stat1 and Stat3 in case of the patients with retinitis and Stat4 in case of the patients with gastroenteritis which aggravates the severity of the disease." (PMID 35538132, 2022).
IPEX syndrome (5 papers, 2016 to 2025). "Here, HIES including STAT3 deficiency and STAT3-related deficiency is also associated with activated Th2 responses and decreased Th17 generations; CARD11 deficiency, IPEX syndrome, STAT5B deficiency, and OS affect Treg diversity or function that regulates Th2 immunity." (PMID 36140582, 2022). "A decreased frequency of FOXP3+ Tregs has been observed in the peripheral blood of some, but not all, STAT3 GOF patients, and taken together with the overlapping clinical features in STAT3 GOF and IPEX syndrome, it has been suggested that this disease falls within the spectrum of Tregopathies." (PMID 36136607, 2022).
ischemic disease (5 papers, 2013 to 2024). Lack of blood supply to an area of the body, resulting in impairment of tissue oxygenation. "Previous studies have shown that mutations in STAT3 are associated with neurodegenerative diseases such as AD, whereas SP1 is associated with cardiovascular diseases, and NFkB is associated with hypoxic and ischemic disease." (PMID 39872979, 2024). "For example, Stat3 is protective in various ischemic diseases including retinal I/R injury." (PMID 23800383, 2013). "Our study indicated that AS-IV is a key regulator of NO and angiogenesis through the JAK2/STAT3 and ERK1/2 pathways, which provides a mechanistic basis for the potential use of this compound in the treatment of clinical ischemic diseases." (PMID 24135938, 2013).
leiomyoma (5 papers, 2016 to 2025). A well-circumscribed benign smooth muscle neoplasm characterized by the presence of spindle cells with cigar-shaped nuclei, interlacing fascicles, and a whorled pattern. "Sections from the myometrium of the control group and the leiomyoma tissue of the case group were subjected to immunohistochemical staining for STAT-3 and IL-26." (PMID 40943781, 2025). "In this study, we investigated the expression levels of STAT-3 in uterine leiomyomas and evaluated the potential role of this transcription factor in fibroid pathogenesis." (PMID 40943781, 2025). "In particular, STAT-3 inhibitors are thought to be effective for hormone-independent treatment of fibroids." (PMID 40943781, 2025). "Chegini reported that IL-6 increases proliferation and fibrotic response in leiomyoma cells via STAT-3." (PMID 40943781, 2025). "Leiomyoma sections showed strong staining for STAT-3 and IL-26 compared with that in the normal myometrium." (PMID 40943781, 2025). "This study evaluated the expression of STAT-3 and IL-26, two early components of the relevant signaling pathways in leiomyoma tissue in uterine fibroid development; some limitations should be emphasized." (PMID 40943781, 2025). "Expression of phosphorylated STAT3 (pSTAT3) was significantly higher in immortalized leiomyoma cells cocultured with adipocytes and leptin-treated primary cells." (PMID 36771423, 2023). "We previously found that leptin promotes human leiomyoma cell proliferation via the JAK/STAT3 and MAPK/ERK pathways." (PMID 37628676, 2023). "In our previous publication we have demonstrated that leptin treatment increased pSTAT3/STAT3 signaling in immortalized leiomyoma cells." (PMID 36771423, 2023). "A third study showed a trend for Increased VEGF, COX1/2, and STAT3 levels in patients with FIGO type 3 fibroids." (PMID 37108180, 2023). "To further understand the effect of adipocyte on JAK2/STAT3 signaling in leiomyoma development, we cocultured primary and immortalized myometrium and leiomyoma cells with adipocytes and treated the leptin." (PMID 36771423, 2023). "The role of STAT3 in ULM was elucidated in a study in which tyrosine kinase inhibitor reduced leiomyoma cell proliferation in vitro mediated through phosphorylated STAT3 inhibition." (PMID 29201401, 2016). "Leptin exerts these effects by stimulating the phosphorylation of STAT-3 in leiomyoma cells." (PMID 40943781, 2025). "In addition, the microRNA-29 family (specifically, miR-29b) inhibits leiomyoma cell proliferation and migration by suppressing the STAT-3 signaling pathway." (PMID 40943781, 2025). "This study aimed to immunohistochemically detect STAT-3 and IL-26 expression in leiomyoma tissues and determine whether these signaling pathways play a role in leiomyoma pathophysiology." (PMID 40943781, 2025). "Leptin treatment has previously been shown to augment the effect of STAT3 and ERK inhibitors in leiomyoma cells." (PMID 36771423, 2023). "We sought to investigate the effect of STAT3, ERK, and AKT inhibitors in leiomyoma cells cocultured with adipocytes." (PMID 36771423, 2023). "The effects of STAT3, ERK, and AKT inhibitors were assessed in leiomyoma cell lines additionally cultured with adipocytes." (PMID 36771423, 2023). "The purpose of this study was to investigate the effect of STAT3, ERK, and AKT inhibitors on TGF-β3 and VEGF-A expression in leiomyoma cells cocultured with adipocytes and treated with leptin." (PMID 36771423, 2023). "We sought to investigate the effect of STAT3, ERK, and AKT inhibitors in PCNA and TNF-α expression in leiomyoma cells cocultured with adipocytes and leptin treatment." (PMID 36771423, 2023). "Additionally, inhibitors of MAPK/ERK, JAK2/STAT3, and PI3k/AKT leptin receptor pathways are more effective in leiomyoma cells cocultured with adipocytes." (PMID 36771423, 2023).
leiomyoma (continued). "Protein expression levels of phosphorylated ERK1/2/total ERK1/2, phosphorylated STAT3/total STAT3, and phosphorylated AKT1/2/3/total AKT1/2/3 were quantified using immunoblotting in immortalized and primary leiomyoma and myometrial cells cocultured with human adipocytes and treated with leptin." (PMID 36771423, 2023). "Furthermore, adipocyte coculture and leptin treatment increases leiomyoma cells growth through activation of MAPK/ERK, JAK2/STAT3, and PI3k/AKT signaling pathways." (PMID 36771423, 2023). "Furthermore, leptin treatment augmented the effect of STAT3 and ERK inhibitors in human leiomyoma cells." (PMID 36771423, 2023). "Further investigation into the effect of MAPK/ERK, JAK2/STAT3, and PI3k/AKT inhibitors in adipocyte-mediated leiomyoma growth could lead to viable therapeutic strategies for uterine leiomyomas." (PMID 36771423, 2023). "Finally, STAT3, ERK, and AKT inhibitor treatment suppressed PCNA, TNF-α, TGF-β3, and VEGF-A intracellular staining intensity in both adipocyte coculture and leptin treated leiomyoma cells." (PMID 36771423, 2023).
malignant pleural mesothelioma (5 papers, 2016 to 2024). A malignant neoplasm that arises from mesothelial cells in the pleura and shows a diffuse growth pattern. "Similarly, in malignant pleural mesothelioma, the STAT3- nuclear factor-kappa B/DNA Damage Inducible Transcript 3/enhancer-binding protein beta (STAT3-NF-kB/DDIT3/CEBPβ) axis was demonstrated to regulate ALDH1A3 expression and reduce sensitivity to pemetrexed + cisplatin treatment." (PMID 36672441, 2023). "In resistant malignant pleural mesothelioma cells, the Ras/ERK1/2 axis promotes the phosphorylation of STAT3 on serine 727 and increases the transcription of IDO; this event is prevented by ZA and reduces the ex vivo expansion of immunosuppressive Treg cells." (PMID 26980746, 2016).
metastatic prostate carcinoma (5 papers, 2013 to 2024). A carcinoma that arises from the prostate gland and has spread to other anatomic sites. "Therefore, selected inhibitors of NF-κB and signal transducer and activator of transcription 3 (STAT3) signaling pathways have been tested to increase the effectiveness of treatment of metastatic prostate cancer." (PMID 29072623, 2017). "In the integrative network for metastatic prostate cancer STAT3 may be the most important key regulator based on our network analysis, the literature and the results from the survival analysis (highest MST and least BCR events in the group with high STAT3 expression)." (PMID 28005952, 2016). "Among these elements are two TFs (PGR and HOXD10) in the primary and three TFs (STAT3, JUN and JUNB) in the metastatic prostate cancer network." (PMID 28005952, 2016). "Among these, SOX4, STAT3 and STAT5B are known regulators of metastatic prostate cancer through the regulation of genes involved in miRNA processing, transcriptional regulation, and developmental pathways." (PMID 23782521, 2013).
Netherton syndrome (5 papers, 2019 to 2025). Netherton syndrome (NS) is a skin disorder characterized by congenital ichthyosiform erythroderma (CIE), a distinctive hair shaft defect (trichorrhexis invaginata; TI) and atopic manifestations. "While ALOX12B-ARCI shares surface phenotypic features with syndromic ichthyoses, such as Netherton syndrome or STAT3 HIES, its immunological footprint appears milder, incomplete, and most consistent with secondary immune dysregulation." (PMID 41346588, 2025). "Atopic dermatitis (AD) is reported to be correlated with AD‐HIES (job's syndrome), IPEX, Netherton syndrome, PGM3 deficiency, DOCK8 deficiency, STAT3 GOF, Omenn syndrome, activated leukocyte cell adhesion molecule (ALCAM), and hypereosinophilia." (PMID 37102642, 2023).
oligodendroglioma (5 papers, 2020 to 2025). A well-differentiated (WHO grade II), diffusely infiltrating neuroglial tumor, typically located in the cerebral hemispheres. "For example, p-STAT3 expression was detected in 38% of oligodendroglioma patients (n = 16), 40% of anaplastic oligodendroglioma (AO) patients (n = 15), and 100% of WHO grade II MOA patients (n = 6)." (PMID 36923251, 2023).
Opportunistic infection (5 papers, 2011 to 2024). An infection that is caused by a pathogen that would generally not be able to cause an infection in a host with a normal immune system. "In our patients, mutations in NFKB1 and STAT3 also led to opportunistic infections, including Mycobacterium avium intracellulare, JC virus-induced progressive multifocal leukoencephalopathy, Pneumocystis jirovecii pneumonia, and Molluscum contagiosum." (PMID 27379089, 2016). "Also, patients with STAT3-deficient HIES show defective lung tissue healing, which is a major determinant of morbidity and mortality by favoring secondary opportunistic infections." (PMID 37982695, 2024). "Thus if STAT3 signaling is defective, as in HIES, Th17 differentiation is suppressed and there is resultant susceptibility to opportunistic infection." (PMID 22126402, 2011).
prion disease (5 papers, 2018 to 2024). A transmissible disease that is caused by a protein that is able to induce abnormal folding of normal cellular proteins, leading to characteristic spongiform brain changes, which are associated with neuronal loss without an inflammatory response. "Because reactive astrocytes associated with prion disease are detrimental to neurons, the delay in the incubation time could be attributed to an attenuation of a STAT3-mediated activation of astrocytes in ST6Gal1-KO mice." (PMID 36452458, 2022). "For example, Stat3 showed increased phosphorylation in mouse brains infected with prions, suggesting its potential roles in pathogenesis of prion disease." (PMID 31959236, 2020). "This suggests that the expression of sCJD-specific miRNAs is under STAT3 regulation, which has been described as activated not only in experimental models of prion diseases, but also in sCJD post-mortem tissue." (PMID 29357384, 2018).
prostatic intraepithelial neoplasia (5 papers, 2011 to 2021). "Experiments have documented that ETK overexpression can increase proliferation in mouse prostate epithelium and result in development of prostatic intraepithelial neoplasia (PIN) by increasing AKT and STAT3 activity." (PMID 24606948, 2014). "It has been shown that ETK overexpression can increase proliferation in mouse prostate epithelium and result in development of prostatic intraepithelial neoplasia (PIN) partly by increasing AKT and STAT3 activity." (PMID 21408190, 2011).
pulmonary tuberculosis (5 papers, 2020 to 2023). A bacterial infection that affects the lungs and is caused by Mycobacterium tuberculosis. "Phosphorylation of STAT3 has been found in studies to aggravate lung injury in mice with T2DM-associated pulmonary tuberculosis." (PMID 36818229, 2023). "In pulmonary TB, the high concentrations of IL-6/IL-10 and STAT-3 led to the impaired function of T cells." (PMID 36439164, 2022).
red cell aplasia (5 papers, 2013 to 2026). "Immunological features of acquired pure red cell aplasia: Specific human leucocyte antigen alleles, signal transducer and activator of transcription 3 mutations and a unique T- cell receptor beta motif." (PMID 41940437, 2026).
schwannoma (5 papers, 2017 to 2026). A benign, usually encapsulated slow growing tumor composed of Schwann cells. "PAK2 modulates STAT3 signaling to enhance cyclin D1 expression; activates Wnt/β-catenin signaling in Schwannoma cells." (PMID 39769207, 2024). "MMP-9 cleaves N-cad to drive schwannoma proliferation through IL-6/STAT3 and NF-κB signaling." (PMID 41756440, 2026). "Analysis of phospho-receptor tyrosine kinase and phospho-kinases proteome profiler arrays revealed that schwannomas consistently had higher levels of phosphorylated PDGFRα, PDGFRβ, SRC, MEK and STAT3 compared with control primary HSC." (PMID 28427224, 2017). "Schwannomas exhibited averaged 6.6 times higher PDGFRα phosphorylation, 5.4 times higher PDGFRβ phosphorylation, 30 times higher SRC phosphorylation, 5.6 times higher MEK phosphorylation and 7.4 times higher STAT3 phosphorylation compared with control primary HSC." (PMID 28427224, 2017).
sinusitis (5 papers, 2012 to 2025). An acute or chronic inflammatory process affecting the mucous membranes of any sinus cavity. "STAT3 (Y705) was similarly phosphorylated, and p-STAT3 levels were lower in IP cases than in chronic sinusitis cases." (PMID 37109043, 2023).
Sjögren's syndrome (5 papers, 2012 to 2025). "Not much is known about NK cells in Sjögren's syndrome, so the correlation with basal phosphorylation of ERK, STAT1 Y701, and STAT3 Y705 in NK cells is especially interesting." (PMID 30846988, 2019).
skin infection (5 papers, 2013 to 2025). An inflammatory process affecting the skin, caused by bacteria, viruses, parasites, or fungi. "Dominant negative mutation of the STAT3 gene is one innate defect associated with AD and severe skin infection susceptibility from infancy." (PMID 28081250, 2017). "Understanding STAT3 dependent innate signaling mechanisms may offer new means of identifying individuals susceptible to severe skin infection, and new opportunities for their treatment." (PMID 25419841, 2014). "We evaluated skin infection with the current smallpox vaccine, ACAM-2000, in immunosuppressed mice with combined cutaneous deficiency in filaggrin and STAT3." (PMID 28081250, 2017). "Humans with a dominant negative mutation in STAT3 are susceptible to severe skin infections, suggesting an essential role for STAT3 signaling in defense against cutaneous pathogens." (PMID 25419841, 2014). "Additionally, patients with a genetic defect in STAT3 that results in an absence of Th17 cells are more susceptible to S. aureus skin infections, again demonstrating an important role for Th17 cells in immune defense against S. aureus cutaneous infections." (PMID 24098366, 2013).
staphylococcal infection (5 papers, 2014 to 2025). An infection caused by Staphylococcus. "IL-17 stimulation is required to produce antibodies against staphylococci 33, which increases the risk of severe staphylococcal infections in patients with anti-IL-17 antibodies, like those with deficits in the STAT3 signaling pathway." (PMID 39836835, 2024). "Further research should focus on the relevance of these factors during staphylococcal infection in humans, taking into account the cell type–specific response by ubiquitously deficient STAT3 signaling." (PMID 37982695, 2024). "Elevated plasma levels of MMP9 in STAT3-deficient patients and its role in degradation of extracellular matrix during tissue remodeling led us to hypothesize that MMP9 may be differentially expressed in myeloid STAT3-deficient as compared with WT mice during pulmonary staphylococcal infection." (PMID 37982695, 2024). "In this study, we investigated the pro- and anti-inflammatory effects of staphylococcal infection of bone marrow–derived macrophages (BMDM) from myeloid STAT3 knockout (KO) mice compared with wild-type (WT) mice." (PMID 37982695, 2024). "Autosomal-recessive ZNF341 deficiency leads to reduced cytokine signaling via STAT3 and resembles STAT3-HIES by displaying similar multisystemic features (e.g., bone fractures, retention of primary teeth, facial dysmorphism) but also staphylococcal infections." (PMID 38720948, 2024). "STAT3 is a relevant modifier of the inflammatory response of macrophages during staphylococcal infection, but not during general macrophage differentiation." (PMID 37982695, 2024). "Overall, our data show that lack of STAT3 in murine BMDM shifts the macrophage phenotype to a hyperinflammatory phenotype during staphylococcal infection." (PMID 37982695, 2024).
tauopathy (5 papers, 2020 to 2025). Neurodegenerative disorders involving deposition of abnormal tau protein isoforms (tau proteins) in neurons and glial cells in the brain. "In contrast, MG2 and MG4, disease-associated cells induced by tauopathy, exhibit higher levels of proinflammatory genes like Apoe, Spp1, Nfkb1, and Akt3, as well as STAT3, IL-8, NF-kB, and JAK/STAT signaling." (PMID 37961627, 2023). "Dap12 deletion reduced levels of p-AKT, p-ERK, p-JNK, p-P38, p-NFκB, and p-STAT3 in the tauopathy mouse brain, indicating dampened inflammatory signaling." (PMID 37961627, 2023). "In a word, our study suggests that STAT3 will hopefully serve as a potential pharmacological target for tauopathies treatment." (PMID 33361763, 2020). "Combined with our published data, we conclude that inhibition of NMDAR expression by activation of STAT1 and inactivation of STAT3 may be a general mechanism of the synaptic and cognitive deficits in tauopathies." (PMID 33859760, 2021).